CCDC102B (coiled-coil domain containing 102B)
Description:
During interphase, forms fibers at the proximal ends of centrioles to maintain centrosome cohesion. During mitosis, dissociates from the centrosome following phosphorylation to allow centrosome separation. Contributes to CROCC/rootletin filament formation.
Synonyms: C18orf14; FLJ23594; HsT1731; AN; ACY1L
Tractability: PROTAC: ubiquitination databases record sites on it.
Gene: Protein-coding gene on chromosome 18 (68,715,138 to 69,057,126, forward strand). Ensembl gene ENSG00000150636.
Subcellular location: Cytoplasm, cytoskeleton, microtubule organizing center, centrosome, centriole
Gene Ontology:
Molecular function: protein binding; protein serine/threonine kinase binding
Biological process: centriole-centriole cohesion
Cellular component: centriole
Genetic constraint (gnomAD): Loss-of-function variants: 61 observed, 47.66 expected, observed/expected ratio (o/e) 1.28, 90% interval 1.04 to 1.58. The upper end of that interval is the gene's LOEUF score, 1.58, which puts it in group 6 of 6, group 1 being the genes least tolerant of losing a copy. Missense variants: 542 observed, 525.16 expected, observed/expected ratio (o/e) 1.03, 90% interval 0.96 to 1.11. Synonymous variants: 184 observed, 184.26 expected, observed/expected ratio (o/e) 1, 90% interval 0.88 to 1.13.
Homologues: Orthologues: chimpanzee CCDC102B (98% identical), macaque CCDC102B (93% identical), dog CCDC102B (71% identical), zebrafish si:ch211-14a17.10 (18% identical). Paralogues in human: CCDC102A (43% identical), MYH3 (23% identical), MYH7 (23% identical), MYH10 (23% identical), MYH6 (23% identical), MYH7B (23% identical), MYH1 (22% identical), MYH2 (22% identical), MYH4 (22% identical), MYH13 (22% identical), MYH15 (22% identical), MYH14 (22% identical), and 32 more.
Diseases named in the same sentence as CCDC102B in open-access papers:
CCDC102B is named in the same sentence as 14 diseases in open-access papers, as found by Europe PMC text mining. Sharing a sentence is not in itself a finding about the gene and the disease. The quoted sentences say what the papers report.
myopic maculopathy (4 papers, 2018 to 2025). "In 2018, GWAS analysis of myopic maculopathy performed in a Japanese population identified CCDC102B as a susceptibility gene for myopic maculopathy." (PMID 37627937, 2023). "Regarding genetic factors, CCDC102B is a susceptibility gene for myopic maculopathy in the Japanese population." (PMID 36561853, 2022). "Our two-stage genome-wide association study of myopic maculopathy identifies a susceptibility locus at rs11873439 in an intron of CCDC102B (P = 1.77 × 10−12 and Pcorr = 1.61 × 10−10)." (PMID 29725004, 2018). "In conclusion, we identified a significant association of CCDC102B with the development of myopic maculopathy via two-stage GWAS in a community-based cohort and case-control studies using highly myopic patients." (PMID 29725004, 2018). "Our GWAS using a Japanese cohort showed that CCDC102B, encoding coiled-coil domain-containing 102B, located at chromosome 18q22.1-q22.2, had a genome-wide significant association with myopic maculopathy." (PMID 29725004, 2018). "The significant association of CCDC102B with myopic maculopathy development in highly myopic eyes, even after adjusting for axial length, suggested that CCDC102B contributed to the stage of developing myopic maculopathy rather than the stage of inducing high myopia itself." (PMID 29725004, 2018). "Current research suggests that CCDC102B is primarily involved in the development of myopic macular degeneration and tumorigenesis, while GRIN2B is mainly involved in neurotransmitter transmission." (PMID 39854306, 2025). "CCDC102B is strongly expressed in the retinal pigment epithelium and choroids, where atrophic changes initially occur in myopic maculopathy." (PMID 29725004, 2018). "CCDC102B may thus contribute to the development of diaphragmatic hernia and myopic maculopathy by weakening connective tissue." (PMID 29725004, 2018). "As this deletion can interrupt CCDC102B, CCDC102B may affect both microphthalmia and myopic maculopathy development in eyes." (PMID 29725004, 2018). "Treatments targeting CCDC102B may thus prevent the development of myopic maculopathy and blindness, even after the occurrence of high myopia." (PMID 29725004, 2018). "CCDC102B is a susceptibility gene for myopic maculopathy, but not for myopia." (PMID 37627937, 2023). "The development of myopic maculopathy thus likely exhibits a unique background apart from the development of myopia itself; elucidation of the roles of CCDC102B in myopic maculopathy development may thus provide insights into preventive methods for blindness in patients with high myopia." (PMID 29725004, 2018).
breast carcinoma (2 papers, 2022 to 2023). "Taken together, these results demonstrated that increased expression of CCDC102B was correlated with poor clinical outcomes in breast cancer, suggesting that CCDC102B was associated with increased metastatic ability in breast cancer." (PMID 35957886, 2022). "Si and colleagues claimed that coiled-coil domain containing 102B (CCDC102B) was apparently increased in metastatic lesions in lymph nodes of breast cancer patients." (PMID 36936167, 2023). "We identified CCDC102B, newly described as a tumor-related gene, as a candidate metastasis promoter in breast cancer." (PMID 35957886, 2022). "Taken together, these findings confirmed that high CCDC102B expression promoted breast cancer cell metastasis in vitro and in vivo." (PMID 35957886, 2022). "To explore the role of CCDC102B in breast cancer, we examined the expression of CCDC102B in 212 breast tumor samples and analyzed the correlation between CCDC102B expression and the clinicopathological characteristics of breast cancer patients." (PMID 35957886, 2022). "We further identified that CCDC102B was stabilized by the loss of RACK1, a protein negatively correlated with breast cancer metastasis." (PMID 35957886, 2022). "With analysis of targeted expression of CCDC102B in breast cancer patients with different nodal status, we found significantly higher expression of CCDC102B in LN-positive patients (P=0.0005)." (PMID 35957886, 2022). "In this study, we presented several interesting findings concerning the biological function and regulatory mechanism of CCDC102B in breast cancer." (PMID 35957886, 2022). "On the other hand, the enhancement of the migration of RACK1 knockout breast cancer cells was attenuated by CCDC102B knockout." (PMID 35957886, 2022). "The median survival time of breast cancer patients with high CCDC102B expression was 70.30 months, which was significantly shorter than that of patients with low CCDC102B expression (75.87 months)." (PMID 35957886, 2022). "Functional rescue tests were performed showing that the migration of breast cancer cells was significantly impaired by CCDC102B knockout, while was remarkably enhanced in NF−κB activated cells." (PMID 35957886, 2022). "To further validate the potential significance of CCDC102B in breast cancer metastasis in vivo, we generated an orthotopic xenograft breast cancer model using stable CCDC102B-overexpressing MDA-MB-231 LM2 cells." (PMID 35957886, 2022). "Taken together, our results demonstrated that RACK1 inhibits breast cancer metastasis by decreasing the stability of CCDC102B." (PMID 35957886, 2022). "Increased expression of CCDC102B was required for breast cancer metastasis." (PMID 36936167, 2023). "In addition, the bc-GenExMiner 3.0 database was used to explore the correlation between CCDC102B expression and nodal status in breast cancer patients." (PMID 35957886, 2022). "To investigate the role of CCDC102B in breast cancer migration and metastasis, we analyzed the expression of CCDC102B in breast cancer cells and developed three CCDC102B-overexpressing stable breast cancer cell line models (MDA-MB-231, BT549, and MDA-MB-231 LM2) for in vitro and in vivo studies." (PMID 35957886, 2022). "Additionally, high expression of CCDC102B was correlated with poor clinical outcomes in breast cancer patients." (PMID 35957886, 2022). "Considering that RACK1 decreased the stability of CCDC102B, we hypothesized that RACK1 might exert its effects on breast cancer cell metastasis by regulating the degradation of CCDC102B." (PMID 35957886, 2022). "Based on the TMA data, we analyzed the correlation between CCDC102B expression and the prognosis of breast cancer patients, which showed that CCDC102B was an independent predictive factor of both recurrence-free survival (RFS) and overall survival (OS) (P=0.009 and P=0.002, respectively)." (PMID 35957886, 2022).
breast carcinoma (continued). "However, few studies have focused on the function and mechanism of CCDC102B in the development and metastasis of breast cancer, especially in the early stage of the transition from primary cancer to metastatic tumors." (PMID 35957886, 2022). "Moreover, overexpression of CCDC102B remarkably accelerated tumor growth and lung metastasis in breast cancer xenograft models." (PMID 35957886, 2022). "Increased expression of CCDC102B promoted breast cancer metastasis in vitro and in vivo." (PMID 35957886, 2022). "Gene set enrichment analysis (GSEA) showed that genes with expression changes (fold change > 1.5) were significantly associated with cancer development and metastasis, such as the NF−κB pathway, supporting the role of CCDC102B in breast cancer cell proliferation and metastasis." (PMID 35957886, 2022). "Thus, all of these reports indicate the relationship among RACK1, CCDC102B and the NF-κB pathway, which has important functions in breast cancer metastasis." (PMID 35957886, 2022). "Taken together, our findings uncover a novel role of CCDC102B in breast cancer metastasis." (PMID 35957886, 2022). "As CCDC102B expression is upregulated in breast tumors, the discovery of novel drugs targeting CCDC102B could suppress breast cancer growth and mitigate metastasis." (PMID 35957886, 2022). "Thus, CCDC102B expression is one of the key predictors of early-stage metastasis in breast cancer." (PMID 35957886, 2022). "Taken together, our findings demonstrate that CCDC102B plays a crucial role in promoting early-stage breast cancer metastasis and could serve as a novel predictor of clinical outcomes in breast cancer patients and a potential therapeutic target for mitigating breast cancer metastasis." (PMID 35957886, 2022). "Overexpression of CCDC102B could promote breast cancer metastasis in vitro and in vivo." (PMID 35957886, 2022). "Therefore, CCDC102B could serve as an independent prognostic factor in breast cancer." (PMID 35957886, 2022). "Among these, there was a remarkable linear internal relationship for CCDC102B but non-linear relationships for others with breast cancer patient prognosis." (PMID 36936167, 2023). "In summary, we uncovered the interaction between CCDC102B and RACK1, which could be one of the mechanisms involved in the early-stage metastasis of breast cancer." (PMID 35957886, 2022). "We found that increased CCDC102B expression correlated with poor RFS and OS in breast cancer patients and could promote the migration and invasion of breast cancer cells." (PMID 35957886, 2022). "In this study, we identified CCDC102B via CRISPR/Cas9 screening in vivo and found that it was significantly upregulated in metastatic LNs compared with primary tumors, which led to a poor prognosis in breast cancer patients." (PMID 35957886, 2022). "The negative correlation of RACK1 and CCDC102B expression was not due to repressed transcription, as revealed by qRT–PCR analysis in breast cancer patients (n=177)." (PMID 35957886, 2022). "Thus, the interaction between CCDC102B and RACK1 regulates the metastatic ability of breast cancer." (PMID 35957886, 2022). "Mechanistically, receptor for activated C kinase 1 (RACK1), which was negatively correlated with breast cancer prognosis, bound to the third coiled-coil structure of CCDC102B, which includes two putative KFERQ-like motifs, and participated in the lysosomal degradation of CCDC102B through CMA." (PMID 35957886, 2022).
breast tumor (1 paper, 2022). "IHC staining of a TMA confirmed that CCDC102B was expressed in breast tumor tissues, and semiquantitative scoring revealed that the high expression of CCDC102B was correlated with younger age (P=0.033) and higher histological grade (P=0.019)." (PMID 35957886, 2022).
congenital diaphragmatic hernia (1 paper, 2018). A posterolateral defect of the diaphragm that allows passage of abdominal viscera into the thorax, leading to respiratory insufficiency and persistent pulmonary hypertension with high mortality. "Although the specific roles of CCDC102B have not been reported in any organ to date, one group reported that a 2.7-Mb deletion at chromosome 18q22.1 contributes to congenital diaphragmatic hernia with microphthalmia." (PMID 29725004, 2018).
triple-negative breast carcinoma (1 paper, 2022). An invasive breast carcinoma which is negative for expression of estrogen receptor (ER), progesterone receptor (PR), and human epidermal growth factor receptor 2 (HER2). "When these tumors were divided into luminal A, luminal B, HER2+ and triple-negative breast cancer (TNBC) subtypes, high expression of CCDC102B showed a particularly strong correlation with poor clinical outcome in HER2+ and TNBC." (PMID 35957886, 2022).
tumor (3 papers, 2017 to 2025). "We found that the long tumor diameters and tumor volumes were significantly increased when CCDC102B was overexpressed, while body weight was similar in the two groups." (PMID 35957886, 2022). "Such dedifferentiated PSMC (dPSMC) were apparent within strands of stromal tissue between tumour glands with disorganised isolated PSMC displaying decreased CNN1, CCDC102B and MCAM immunopositivity." (PMID 41378308, 2025). "With little degradation, excess CCDC102B binds with RACK1, which may compete with IKK binding, resulting in NF-κB pathway activation and eventually promoting tumor development or metastasis." (PMID 35957886, 2022).
CCDC102B also shares sentences with these, for which no sentence is quoted: cancer (2 papers); microphthalmia (2); myopia (2); Blindness (1); diaphragmatic hernia (1); familial colorectal cancer (1); lung carcinoma (1); tobacco use disorder (1).